Y_RNA (Y RNA )
Gene: Miscellaneous RNA gene on chromosome 16 (439,297 to 439,397, reverse strand). Ensembl gene ENSG00000201034.
Homologues: Orthologues: chimpanzee Y_RNA (99% identical), macaque Y_RNA (92% identical), guinea pig Y_RNA (90% identical). Paralogues in human: Y_RNA (89% identical), RNY3 (88% identical), RNY3P1 (87% identical), Y_RNA (87% identical), Y_RNA (86% identical), RNY3P11 (85% identical), Y_RNA (85% identical), RNY3P16 (84% identical), Y_RNA (84% identical), RNY3P14 (83% identical), Y_RNA (83% identical), RNY3P2 (82% identical), and 93 more.